LEPROT (leptin receptor overlapping transcript)
Description:
Negatively regulates leptin receptor (LEPR) cell surface expression, and thus decreases response to leptin. Negatively regulates growth hormone (GH) receptor cell surface expression in liver. May play a role in liver resistance to GH during periods of reduced nutrient availability.
Synonyms: OB-RGRP; OBRGRP; VPS55; FLJ90360
Tractability: Antibody: UniProt places it where antibodies can reach, with medium confidence; UniProt predicts a signal peptide or a membrane-spanning region. PROTAC: its protein half-life has been measured.
Gene: Protein-coding gene on chromosome 1 (65,420,587 to 65,436,007, forward strand). Ensembl gene ENSG00000213625.
Subcellular location: Golgi apparatus membrane; Endosome membrane
Subcellular location (Human Protein Atlas): Centrosome
Gene Ontology:
Molecular function: protein binding; signaling receptor binding
Biological process: negative regulation of growth hormone receptor signaling pathway; negative regulation of protein localization to cell surface; negative regulation of receptor signaling pathway via JAK-STAT; positive regulation of establishment of protein localization to mitochondrion; late endosome to vacuole transport via multivesicular body sorting pathway
Cellular component: endosome; Golgi apparatus; endosome membrane; Golgi membrane
Genetic constraint (gnomAD): Loss-of-function variants: 3 observed, 12.55 expected, observed/expected ratio (o/e) 0.24, 90% interval 0.11 to 0.62. The upper end of that interval is the gene's LOEUF score, 0.62, which puts it in group 2 of 6, group 1 being the genes least tolerant of losing a copy. Missense variants: 133 observed, 143.83 expected, observed/expected ratio (o/e) 0.92, 90% interval 0.8 to 1.07. Synonymous variants: 59 observed, 53.51 expected, observed/expected ratio (o/e) 1.1, 90% interval 0.89 to 1.37.
Homologues: Orthologues: chimpanzee LEPROT (97% identical), macaque LEPROT (97% identical), pig LEPROT (97% identical), guinea pig LEPROT (95% identical), dog LEPROT (95% identical), mouse Leprot (95% identical), rat Leprot (94% identical), rabbit LEPROT (89% identical), tropical clawed frog leprot (84% identical), Caenorhabditis elegans C30B5.2 (47% identical), Drosophila melanogaster CG30423 (37% identical). Paralogues in human: LEPROTL1 (68% identical).
Diseases named in the same sentence as LEPROT in open-access papers:
LEPROT is named in the same sentence as 13 diseases in open-access papers, as found by Europe PMC text mining. Sharing a sentence is not in itself a finding about the gene and the disease. The quoted sentences say what the papers report.
Obesity (11 papers, 2012 to 2025). Accumulation of substantial excess body fat. "Numerous studies have been conducted on the association between polymorphism of LEPTIN, LEPR, LEPROT, and human obesity." (PMID 36011333, 2022). "LEPROT is involved in the cell-surface expression of the leptin receptor, regulation of growth hormones linked to obesity in mice, and cell signaling in response to circulating nutrient levels." (PMID 22577559, 2012). "Elevated LEPROT was observed in patients with preoperative obesity (1.53 vs. 1.45, and p = 0.038), and LEPROTL1 was highly expressed in male patients with CP (1.38 vs. 1.20, and p = 0.031)." (PMID 37509115, 2023). "In mice, LEPROT knockdown showed high leptin sensitivity and was resistant to diet-induced obesity, and it was thought to be a candidate for regulating leptin sensitivity." (PMID 36011333, 2022). "Similarly, in our own study investigating human tissues, we observed that LEPROT transcripts are increased in the adipose tissue of patients with obesity compared with lean control patients." (PMID 38716728, 2024). "We detected that individuals with obesity and GI or T2D are characterized by elevated plasma levels of HbA1C and the inflammatory cytokine IL-6, by lower plasma levels of adiponectin, and by higher levels of LEPROT in their adipose tissue." (PMID 38716728, 2024). "Previous studies indicated that LEPROT could negatively regulate the cell surface expression of LEPR and the silencing LEPROT expression in the mouse hypothalamic arcuate nucleus prevented the development of high-fat-diet-induced obesity." (PMID 35223490, 2022). "In contrast, the newly discovered variant at the LEPR/LEPROT locus associated with BMI-AP did not associate with other growth traits reported here, or in previous studies on childhood/adult BMI and obesity." (PMID 31840077, 2019).
breast carcinoma (2 papers, 2021 to 2022). "The association between LEPR or LEPROT level and outcomes of breast cancer patients was further evaluated by Kaplan–Meier survival analysis based on TCGA-BRCA data." (PMID 35223490, 2022). "To further identify the downstream associated genes of breast cancer risk-related variants, we found that 2 cis-eQTL genes (LEPR and LEPROT) were associated with rs4655555 based on the eQTLGen database." (PMID 35223490, 2022). "To evaluate the potential causal function of rs4655555-associated genes in breast cancer risk, based on the TCGA database, we found a higher expression of LEPR and LEPROT in breast cancer tumor tissues compared to that of adjacent normal tissues." (PMID 35223490, 2022). "Leptin receptor overlapping transcript (LEPROT) is reported to be involved in metabolism regulation and energy balance as well as molecular signaling of breast cancer and osteosarcoma." (PMID 34804118, 2021). "The expression pattern of LEPR and LEPROT in breast cancer tissues was analyzed using TCGA data." (PMID 35223490, 2022). "However, the association between LEPROT expression and OS of breast cancer patients was not significant (HR = 1.25, 95% CI = 0.84–1.87)." (PMID 35223490, 2022).
endometrial cancer (2 papers, 2020 to 2021). Primary or metastatic malignant neoplasm involving the endometrium (mucous membrane that lines the endometrial cavity). "Interestingly, LEPROT was observed to differentiate endometrial cancer samples regardless of its grade, while in blood samples it was a gene characteristic of G1 cancer." (PMID 34202922, 2021).
osteosarcoma (2 papers, 2021 to 2023). A usually aggressive malignant bone-forming mesenchymal neoplasm, predominantly affecting adolescents and young adults. "Moreso, aberrant alternative splicing of leptin receptor overlapping transcript (LEPROT) gene is also associated with osteosarcoma progression." (PMID 37755271, 2023).
gastric cancer (1 paper, 2022). A primary or metastatic malignant neoplasm involving the stomach. "DeLong’s tests showed that the efficiency of MYOF was significantly better than that of CLIP1 (P < 0.001) and LEPROT (P = 0.037), and a heatmap showed distinct differences in gene expression profiles between gastric cancer and normal gastric tissue." (PMID 36147922, 2022). "The MYOF, CLIP1, AHNAK, ANXA2, ITPRIPL2 and LEPROT genes in tissues of patients with gastric cancer were found to be altered by amplification, extensive deletion, truncating mutations, splice mutations, missense mutations, and high/low mRNA expression." (PMID 36147922, 2022).
tumor (4 papers, 2017 to 2023). "In line with previous reports, LEPROT was widely expressed in human tissues and was downregulated in tumor tissues." (PMID 34804118, 2021). "Tumor-suppressor genes BAX, CDKN2A, and MSH5 were negatively correlated with LEPROT in multiple cancer types, and most tumor-suppressor genes were suggested to be positively correlated with LEPROT in a gene-consistent way across cancer types." (PMID 34804118, 2021). "As determining components of conducting tumor immune response, infiltrating immune cells were remarkably correlated with LEPROT expression in tumor tissues, suggesting the similar features of LEPROT in tumor immune response." (PMID 34804118, 2021). "In the current study, a positive correlation between LEPROT expression and PD-L1 was observed across all cancer types and indicates a role of LEPROT in tumor escaping in cancers." (PMID 34804118, 2021). "Although, generally, mutations of tumor suppressor genes did not result in the alteration of LEPROT expression, the expression of tumor-suppressor genes is shown to be highly related to LEPROT expression." (PMID 34804118, 2021). "In the current study, we first provide a full description of the LEPROT expression in pan-cancer and their molecular subtypes as well as the correlation between LEPROT and the tumor microenvironment (TME), in particular, the immune cells infiltration and cancer-associated fibroblasts (CAFs)." (PMID 34804118, 2021). "Because of conflicting reports on the impacts of LEPROT on downstream signaling and cancer progression, and the lack of investigation on it, we aimed to illustrate the role of LEPROT in tumor initiation and tumor progression across multiple cancer types by bioinformatic analysis." (PMID 34804118, 2021). "The expression of leptin receptors, including LEPR (1.61 vs. 1.13, and p = 0.046), LEPROT (1.42 vs. 1.04, and p = 0.002), LEPROTL1 (1.31 vs.1.10, and p = 0.036), were elevated in CP tumor tissue compared to normal brain tissue." (PMID 37509115, 2023).
cancer (2 papers, 2021 to 2022). A tumor composed of atypical neoplastic, often pleomorphic cells that invade other tissues. "The pan-cancer mutation spectra of LEPROT indicated a low mutant frequency of LEPROT across all cancer types with the maximal alteration frequency of LEPROT in SARC (only 3.14%)." (PMID 34804118, 2021). "Our study highlights the LEPROT expression as being significantly decreased in 12 cancer types, indicating that loss or downregulation of LEPROT expression could be associated with tumorigenesis in these cancers." (PMID 34804118, 2021). "A recent study identified an aberrant expression of LEPROT in 78.9% cancers compared with corresponding normal tissues." (PMID 35223490, 2022). "LEPROT expression was positively correlated with most oncogenes in a broad spectrum of cancer types, suggesting a role of LEPROT in promoting cancer progression." (PMID 34804118, 2021). "The LEPROT mRNA level was overall positively correlated with the signatures of effect T cells, resident memory T cells, Th1 cells, and CAFs across all cancer types using whole TCGA cancer data sets." (PMID 34804118, 2021). "The negative correlations between the expression of LEPROT and its methylation indicate a regulation of LEPROT by DNA methylation in cancers." (PMID 34804118, 2021). "It revealed LEPROT methylation reduced its expression in most cancer types except for ACC, BLCA, HNSC, KICH, MESO, SKCM, and UCEC." (PMID 34804118, 2021). "The expressions of LEPROT in cancers were compared with corresponding normal tissues across pan-cancer types." (PMID 34804118, 2021). "To understand the role of the aberrantly expressed LEPROT in cancer development, we explored the correlation between the mRNA expression level of LEPROT and commonly reported oncogenes across various cancer types by TIMER2." (PMID 34804118, 2021). "Further evaluation of LEPROT mRNA levels was performed in different molecular subtypes across pan-cancer types." (PMID 34804118, 2021). "LEPROT expression was found to be significantly aberrant in 15/19 (78.9%) cancers compared with corresponding normal tissues; LEPROT was downregulated in 12 cancers and upregulated in three cancers." (PMID 34804118, 2021). "LEPROT is expressed in various tissue and is suggested to be involved in cancer developments but with contradictory roles." (PMID 34804118, 2021). "Therefore, we highlighted the IL6ST/JAK/STAT pathway in the effect of LEPROT in cancer, which was profoundly involved in the proliferation of cancer cells, immune regulation, and CAF activation and function." (PMID 34804118, 2021). "Furthermore, the present study reveals that higher levels of LEPROT correlate with a worse prognosis in several cancers." (PMID 34804118, 2021). "This is the first study to investigate the roles of LEPROT across pan-cancer." (PMID 34804118, 2021). "LEPROT may also serve as a potential prognostic marker or a target in cancer therapy." (PMID 34804118, 2021). "These indicate LEPROT might serve as potential prognostic markers for several cancer types." (PMID 34804118, 2021). "In contrast, LEPROT was found to activate the JAK/STAT pathway and may facilitate cancer development." (PMID 35223490, 2022). "Unexpectedly, the expression of LEPROT was positively correlated with that of DNMT1 and DNMT3A but not DNMT3B in most cancers and was consistently positive-correlated with DNMT2 in all cancers." (PMID 34804118, 2021). "However, a more recent study paradoxically reported that LEPROT could activate the JAK/STAT signaling, which may theoretically facilitate cancer development." (PMID 34804118, 2021). "Results show that the level of LEPROT was consistently positively correlated with that of JAK1, JAK2, and STAT3, which suggested that JAK1/2/STAT3 might be the downstream LEPROT and mediate cancer cell proliferation and TME alterations." (PMID 34804118, 2021). "Moreover, regardless of the regulation of LEPROT in cancer, it maintained a high correlation with the IL6ST/JAK1/2/STAT3 pathway." (PMID 34804118, 2021).
cancer (continued). "Moreover, CAFs, a prominent component of the microenvironment in most types of solid tumors, which are also considered to be involved in TII (Barrett and Puré, 2020), were also shown to consistently positively correlate with LEPROT expression regardless of the cancer types." (PMID 34804118, 2021). "As a result of conflicting reports on the impact of LEPROT on downstream signaling and cancer progression, and the lack of investigation on it, a bioinformatic analysis on LEPROT among multiple cancer types was, therefore, conducted for a broader understanding of the roles of LEPROT in cancers." (PMID 34804118, 2021).
LEPROT also shares sentences with these, for which no sentence is quoted: Breast Invasive Carcinoma (1 paper); chylomicron retention disease (1); familial lipoprotein lipase deficiency (1); Glucose intolerance (1); hyperglycaemia (1); type 1 diabetes (1).